PIEZO1 (piezo type mechanosensitive ion channel component 1 (Er blood group))
Diseases named in the same sentence as PIEZO1 in open-access papers (continued):
Sharing a sentence is not in itself a finding about the gene and the disease.
glioma (continued). "Analysis of transcriptomic data from the following databases: Chinese Glioma Genome Atlas RNAseq, the Cancer Genome Atlas RNAseq, and the GSE16011 database, revealed that Piezo1 expression was shown to be correlated with the clinical and molecular characteristics of glioma." (PMID 36173070, 2023). "A functional enrichment analysis of the China Glioma Genome Atlas (CGGA) dataset and the Gene Set Enrichment Analysis (GSEA) dataset revealed that PIEZO1 acts as a central node in a functional regulatory network that integrates regulators associated with tissue-stiffening molecules." (PMID 36765838, 2023). "The mechanical stiffness of glioma tissues and other factors in the tumor microenvironment, such as extracellular matrix (ECM) remodeling, angiogenesis, and cell migration, may promote tumor progression through Piezo1 activation." (PMID 39539343, 2024). "Piezo1 localizes at the focal adhesions and activates integrin-focal adhesion kinase (FAK) signaling, leading to an increase in matrix stiffness; meanwhile, an enhanced mechanical microenvironment increases Piezo1 expression, thereby promoting glioma invasiveness." (PMID 36230880, 2022). "However, until now, the relationship between PIEZO1 expression and glioma malignancy in human patients has not been studied." (PMID 32999349, 2020).
breast carcinoma (44 papers, 2015 to 2026). "A multidisciplinary approach suggests the importance of cellular geometry in modulating calcium signals in breast cancer cells via the PIEZO1 force sensing channel which is also associated with breast cancer cell plasticity." (PMID 38632473, 2024). "We now show that the activation of PIEZO1 caused pronounced induction of the EPI-MES marker SERPINE1 in breast cancer cells." (PMID 38632473, 2024). "In this study, we investigated the underlying role of Piezo1 activation in the effects of hyperthermia therapy on breast cancer cells and explored the underlying mechanisms." (PMID 38463518, 2024). "This study aims to explore the potential role of Piezo1 activation in the hyperthermia therapy of breast cancer cells and investigate the underlying mechanisms." (PMID 38463518, 2024). "In breast cancer, high expression of Piezo1 in the primary breast tumor was reported to associate with increased hazard ratio and corresponding shorter overall survival time." (PMID 38463518, 2024). "Accordingly, elevated PIEZO1 is associated with 35% poorer survival of patients with breast cancer." (PMID 41779857, 2026). "Furthermore, in this study, Piezo1 was associated with shorter survival times for breast cancer patients." (PMID 34831037, 2021). "Moreover, higher speed of cell migration upon Piezo1 inhibition has been directly linked to increased FA turnover in breast cancer cells." (PMID 34822717, 2021). "Next, we explored whether PIEZO1 level is associated with breast cancer patient survival." (PMID 38398074, 2024). "Further investigation revealed that the mechanosensitive ion channel Piezo1 was activated on breast cancer cells in narrow microchannels, thereby accelerating calcium influx." (PMID 41356797, 2026). "In conclusion, our data revealed that breast cancer cells dynamically modulated Piezo1 activity in response to mechanical cues, with Piezo1-mediated extracellular Ca2+ influx emerging as a critical regulator of nuclear morphological adaptations." (PMID 41356797, 2026). "Here, we demonstrate that PIEZO1 regulates the proliferation, migration, and survival of breast cancer cells in a mechanosensitive environment-dependent manner." (PMID 42268805, 2026). "The Piezo1 expression was significantly up-regulated in pancreas cancer, breast cancer, brain cancer, liver cancer and ovary cancer." (PMID 41585435, 2026). "Chemosensitivity assays further revealed that although PIEZO1 silencing sensitized the breast cancer cells to doxorubicin in static conditions, it enhanced drug resistance in anoikis-inducing conditions." (PMID 42268805, 2026). "Tumor cells encounter diverse mechanical forces during cancer progression, and the mechanosensitive ion channel PIEZO1 governs how breast cancer cells adapt to these cues, thereby shaping their metastatic potential." (PMID 42268805, 2026). "Analysis of clinical datasets revealed differential regulation of PIEZO1 between primary and metastatic breast cancers." (PMID 42268805, 2026). "Breast cancer cells under solid stress compression also exhibited enhanced invasion through Piezo1 activation." (PMID 40371393, 2025). "Breast Cancer: In breast cancer, Piezo1 exerts little influence on cell proliferation or cell-cycle progression but acts as a pivotal mechanosensitive node that regulates migration and invasion." (PMID 40821847, 2025). "Research has demonstrated that Piezo1 forms functional ion channels in MCF-7 breast cancer cells, and its elevated expression is associated with reduced overall survival in breast cancer patients." (PMID 40110186, 2025). "Aggressive breast cancer cells under solid stress compression have been found to show increased invasion through the activation of Piezo1 which led to increased actin protrusions and matrix metalloproteinase (MMP) activity." (PMID 40371393, 2025).
breast carcinoma (continued). "In breast cancer, PIEZO1 activation via YODA1 triggers epithelial–mesenchymal plasticity (EMP), a key step in metastasis and therapy resistance, by remodelling calcium signalling in response to shape changes." (PMID 40806720, 2025). "MTT assays showed that Piezo1 knockdown significantly reduced the inhibitory effect of ES-generated CM on breast cancer cell viability, indicating Piezo1’s essential role in MSC response to ES and tumor-suppressive CM production." (PMID 39940798, 2025). "Piezo1, a mechanosensitive ion channel, plays a significant role in breast cancer progression by enabling cells to detect and respond to mechanical cues." (PMID 40110186, 2025). "Piezo1 modulates breast cancer metastases in the bone by affecting osteoclast and osteocyte activity." (PMID 38390363, 2024). "Stemming from our results of differential PIEZO1 expression levels in different subtypes of breast cancer, we then divided the TCGA cohort into breast cancer subtypes characterized by HR status and HER2 status to examine survival." (PMID 38398074, 2024). "To investigate the potential role of Piezo1 in breast cancer, we first examined the expression of Piezo1 in various breast cancer cells." (PMID 38463518, 2024). "Collectively, our results demonstrate that HR-negative breast cancer subtypes have increased PIEZO1 expression compared to HR-positive subtypes." (PMID 38398074, 2024). "We further investigated the potential effect of Piezo1 activation on hyperthermia therapy of breast cancer." (PMID 38463518, 2024). "In breast carcinoma, Piezo1 and Piezo2 were studied in various different cell lines, with positive expression in all of them." (PMID 39001475, 2024). "The use of these data enabled us to conduct a large-scale analysis of survival outcomes by PIEZO1 expression in breast cancer patients." (PMID 38398074, 2024). "Previously, we have shown that Piezo1 mediates cell migration of breast cancer cells in response to compression." (PMID 38339025, 2024). "Overall, the use of a bioinformatic approach using multiple publicly available datasets enabled us to make inferences regarding the role of PIEZO1 in breast cancer across a large set of patients." (PMID 38398074, 2024). "We conducted various bioinformatic analyses on PIEZO1 in breast cancer, using publicly available online datasets from The Cancer Genome Atlas and GSE3494." (PMID 38398074, 2024). "In the current study, the breast cancer cells, 4T1 cells, were transfected by Piezo1 siRNA or administrated with the Piezo1 agonist Yoda1, followed by exposure to heat stress." (PMID 38463518, 2024). "Our findings demonstrate the clinical relevance of the PIEZO1 ion channel in breast cancer and highlight the importance of PIEZO1 expression on patient survival and its potential as a prognostic biomarker in HR-negative breast cancer patients." (PMID 38398074, 2024). "The photothermal conversion efficiency of TiCN was determined and the Piezo1-specific agonist significantly enhanced the antitumor effect of TiCN, indicating the excellent potential of Piezo1 activation in breast cancer treatment." (PMID 38463518, 2024). "When comparing Caucasian patients (White) with African American patients (Black) with HR-negative breast cancer, interestingly, our results demonstrated that Black patients had higher PIEZO1 expression levels than White patients (p = 0.002)." (PMID 38398074, 2024). "Results showed that the specific agonist of Piezo1 ion channel (Yoda1) aggravated the cell death of breast cancer cells triggered by heat stress in vitro." (PMID 38463518, 2024). "The first study, employing cell lines from normal breast and breast cancer, found increased Piezo1 expression in tumor cells compared with normal cells." (PMID 39001475, 2024). "We further identified that PIEZO1 activation induces features of epithelial-to-mesenchymal plasticity in breast cancer cells." (PMID 38632473, 2024).
breast carcinoma (continued). "To gain insight into the role of mechanosensation in breast cancer, we investigated the role of the PIEZO1 mechanosensory ion channel on breast cancer survival." (PMID 38398074, 2024). "First, we examined the PIEZO1 expression levels in primary tumors among different subtypes of breast cancer in the TCGA cohort." (PMID 38398074, 2024). "Based on previous literature investigating prognostic indicators in breast cancer, we used bc-GenExMiner whole-cohort data to determine the PIEZO1 expression levels throughout different values of the Nottingham Prognostics Index (NPI)." (PMID 38398074, 2024). "Through pathway enrichment analysis and correlation detection using KEGG and Wiki databases, it was found that Piezo1 potentially facilitates the growth of breast cancer by modulating the purine metabolism of GUK1, POLD1 and APRT." (PMID 38690080, 2024). "Taken together, these results suggest that Piezo1 regionally activation is a potential therapeutic strategy to improve breast cancer." (PMID 38463518, 2024). "The breast cancer patients of the whole TCGA cohort were divided into high or low PIEZO1 groups based on a median cutoff." (PMID 38398074, 2024). "An analysis of breast cancer data from The Cancer Genome Atlas (TCGA) was conducted to investigate PIEZO1 expression levels and correlation to survival, followed by validation in an independent dataset, GSE3494." (PMID 38398074, 2024). "Altogether, these results indicated the potential role of Piezo1 activation in heat stress-induced breast cancer cell injury." (PMID 38463518, 2024). "Our study revealed that Piezo1 activation aggravated the injury of breast cancer cells under the setting of hyperthermia therapy." (PMID 38463518, 2024). "Our study, in conjunction with past studies, exemplifies the importance of mechano-signaling, and specifically the PIEZO1 ion channel, in the clinical outcomes of breast cancer patients." (PMID 38398074, 2024). "Collectively, our results suggest how shape-induced changes in cellular signaling and epithelial-mesenchymal plasticity intersect with the PIEZO1 force channel in breast cancer cells." (PMID 38632473, 2024). "The idea that PIEZO1 has differential functions in varying subtypes of breast cancer is further supported by previous literature on PIEZO1 in breast cancer." (PMID 38398074, 2024). "The Piezo1 dependent on caveolae is responsible for both the invasion and migration of breast cancer cells MDA-MB-231." (PMID 36837670, 2023). "On the other hand, it has also been shown that Piezo1 activation can attenuate the blebbing mechanism in breast cancer cells, this type of migration is observed in some other cancers." (PMID 37762011, 2023). "The role of Piezo1 in modifying the proliferation rate and cell cycle of breast cancer cells is controversial." (PMID 36837670, 2023). "On the other hand, in a highly metastatic breast cancer cell line, Piezo1 knockdown was shown to promote migration in an unconfined environment, while impeding confined migration." (PMID 38132106, 2023). "Piezo1 channels are overexpressed in MCF-7 breast cancer cells and are also shown to contribute to the migration, proliferation, and invasion of several cancer cell lines." (PMID 35884459, 2022). "Compared with the corresponding para-carcinoma tissues, Piezo1 is highly expressed in clinical hepatic carcinoma, breast cancer, and pancreatic cancer tissues." (PMID 36230880, 2022). "Blocking functional Piezo1 channels through GsMTx4 decreases the mobility of MCF-7 breast cancer cells." (PMID 35884459, 2022). "Our study confirmed that Piezo1 channels are also essential in mediating the compression-enhanced invasion of breast cancer cells." (PMID 34979904, 2022). "Here, we demonstrate that thrombin induces blebbing in breast cancer cells, and that contact compression or stimulation with the small molecule Yoda1, a Piezo1 agonist, can suppress dynamic blebbing." (PMID 35274124, 2022).
breast carcinoma (continued). "In particular, mechanical compression of breast cancer cells stimulates Ca2+ influx through Piezo1, leading to Src/ERK pathway activation, invadopodia formation, increased matrix degradation and enhanced cell invasion." (PMID 36158191, 2022). "It has been found that Piezo1 channels play essential roles in diverse physiological and pathological processes including cell migration, and the Piezo1 mRNA expression level is highly correlated with the survival time of breast cancer patients." (PMID 34979904, 2022). "Meanwhile, extrusion pressure enhances the aggressiveness of breast cancer cells by increasing Ca2+ influx mediated by Piezo1 and activating downstream Src signaling transduction." (PMID 36230880, 2022). "Taken together, our data indicate that mechanical compression activates Piezo1 channels to mediate enhanced breast cancer cell invasion, which involves both cellular events and matrix degradation." (PMID 34979904, 2022). "Inhibiting Piezo1 blocked the mechanically sensitive ion channel and resulted in the decrease of the migration potential of breast cancer cells, underscoring a possible role of Piezo1 in invasion and metastasis." (PMID 36230880, 2022). "A novel combined therapy was tested in the present study, aiming to enhance osteocytes’ beneficial response to LMHF mechanical stimulation through Piezo1 activation in regulation of osteoclastogenesis and breast cancer migration." (PMID 35884459, 2022). "Numerous studies have investigated the effects of LMHF vibration and the roles of Piezo1 on breast cancer cells separately." (PMID 35884459, 2022). "In breast cancer, Piezo1 initiates Akt/mTOR signaling, a pathway responsible for regulating cell motility and survival." (PMID 34831037, 2021). "Evidence has shown that expression of PIEZO1 increased in multiple malignant diseases including bladder carcinoma, synovial sarcoma, osteosarcoma, breast cancer and gastric cancer." (PMID 32999349, 2020). "PIEZO1 is a mechanosensory ion channel with oncogenic function in breast cancer, especially in metastasis and has been examined as a potential therapeutic target." (PMID 30658617, 2019). "For example, while the P50 is typically reported to be ~ −30 mmHg for heterologously expressed Piezo1 in HEK293t cells, in neural stem cells, the P50 was ~−13 mmHg, whereas the P50 was ~−40 mmHg in the breast cancer cell line MCF-7." (PMID 26646186, 2015). "Together, these findings uncover a dual, stage-specific role for PIEZO1 in breast cancer, in which optimal PIEZO1 activity sustains proliferation and invasion, whereas PIEZO1 loss enhances cell survival under mechanostress, thereby potentiating metastatic dissemination." (PMID 42268805, 2026). "Next, we investigated whether there were differences in PIEZO1 expression in primary tumors between different American Joint Committee on Cancer (AJCC) stages in the whole breast cancer cohort." (PMID 38398074, 2024). "The results showed that Piezo1 could aggregate the heat-induced injury of 4T1 cells, indicating that Piezo1 can be a promising target for the treatment of breast cancer with heat therapy." (PMID 38463518, 2024). "In contrast, it was identified as a tumour-suppressor in cadmium-induced breast cancer whereas miR-4707-3p was reported in oesophageal carcinoma. miR-10b-5p was reported as a regulator of PIEZO1 in breast cancer and as a tumour-suppressor in primary hepatic carcinoma." (PMID 38368395, 2024). "We investigated whether the PIEZO1 prognostic value in HR-negative breast cancer enhances with clinical characteristics such as stage, menopause status, and race in the TCGA cohort." (PMID 38398074, 2024). "Therefore, it would be interesting to further investigate the connections between PIEZO1 and cytoskeleton remodeling, cellular metabolism, and metastasis in breast cancer." (PMID 38398074, 2024). "Further studies investigating the mechanistic roles of PIEZO1 in breast cancer are warranted." (PMID 38398074, 2024).